UBTFL6 (UBTF like 6 (pseudogene))
Gene: Unprocessed pseudogene on chromosome 2 (97,636,780 to 97,637,803, reverse strand). Ensembl gene ENSG00000228970.
Subcellular location: Nucleus